MMP2 (matrix metallopeptidase 2)
Diseases named in the same sentence as MMP2 in open-access papers (continued):
Sharing a sentence is not in itself a finding about the gene and the disease.
prostate carcinoma (continued). "In case of LNCaP, SFMBT2 interacts with YY1 and represses MMP2, MMP3, and MMP9 and inhibits invasion and migration of prostate cancer cells, and illustrating both pro and anti-role of YY1 in prostate cancer growth." (PMID 31824839, 2019). "Studies in prostate cancer demonstrated that overexpressed MAP2K4 promotes prostate cancer metastasis through HSP27 upregulation, which mediates MMP-2 upregulation." (PMID 31761784, 2019). "EGCG (20 μM) reduce the activity of MMP-2 and MMP-9 in prostate cancer cells and decrease the expression of MMP-9 in bladder cancer cells." (PMID 31781485, 2019). "In conclusion, our data suggested that HDGF knockdown inhibits cellular migration and invasion in vitro of prostate cancer via modulating epithelial-mesenchymal transition (EMT) signaling pathway, as well as MMP2 and MMP9 signaling pathway." (PMID 29300772, 2018). "In particular, expression and activity of gelatinases, MMP-2 (72 kDa) and MMP-9 (92 kDa) have been shown to be significantly up-regulated in a variety of cancers, including prostate cancer." (PMID 30197761, 2018). "In another study, α-solanine down-regulated oncogenic microRNA-21 expression by decreasing MMP-2/9 expression via the ERK and PI3K/Akt signal pathway suppressed by human prostate cancer cell (PC-3) invasion and upregulated of tumor suppressor microRNA-138." (PMID 29799481, 2018). "In contrast, TA treatment of 20 μM inhibited the expression of MMP2 and MMP9, the key downstream proteins that drive the EMT in prostate cancer." (PMID 29518944, 2018). "Our findings confirm that Ang1–7 can also modulate the activity of both gelatinases A and B in prostate cancer cells, that MMP-9 activity was upregulated in DU-145 and downregulated in PC3, and that MMP-2 levels were suppressed in LNCaP and PC3 cells." (PMID 30361641, 2018). "Further, it has been shown that β‐hCG promotes the invasion of prostate cancer cells by activating the expression of ERK1/2 and MMP‐2 and decreasing the expression of E‐cadherin in prostate cancer cells and showed poor prognosis of the disease." (PMID 29460395, 2018). "It has revealed that MMP2 and MMP9 are correlated with the invasive and metastatic phenotypes of prostate cancer cells." (PMID 29300772, 2018). "The ZR30-mediated inhibition of MMP2 activation in GBM cells was similarly observed in other human cell lines of cervical cancer, prostate cancer stroma and metastatic prostate cancer (lanes 5-10)." (PMID 29290950, 2017). "Elevated levels of MMP-2 and MMP-9 are observed in prostate cancer and correlate with increased metastasis." (PMID 28257035, 2017). "Thus, prostate cancer may be conversely responsible for lower gene/protein expression of MMP2." (PMID 28445160, 2017). "The levels of MMP‐2 and MMP‐9 expression are considered biomarkers for judging the malignancy of prostate cancer progression and evaluating therapeutic effects." (PMID 28846829, 2017). "Quercetin has been proved to downregulate MMP-2 and MMP-9 protein expression in prostate cancer cells." (PMID 28811592, 2017). "The H2S donors Diallyl(di)sulfide also reduces MMP-2 and MMP-9 activities in human LNCaP prostate cancer cells and in an animal model of lung fibrosis." (PMID 27362269, 2016). "Other studies also consistently show that inhibition of MMP-2 and MMP-9 expression suppresses the metastatic potential of prostate cancer cells." (PMID 27340776, 2016). "In conclusion, our study provides evidence that SFMBT2 regulates prostate cancer metastasis either by direct repression of YY1 target genes such as MMP-9, MMP-26, and N-CoR and by indirect regulation of MMP-2, MMP-3, and KAI1 gene expression." (PMID 27340776, 2016). "We observed similar findings in prostate cancer lines: ELK1-shRNA strongly inhibited AR-negative cell migration/invasion and MMP-2/MMP-9 expression (unpublished data)." (PMID 26342199, 2015).
prostate carcinoma (continued). "Considering the role of gelatinases in prostate cancer invasion, we also analysed the expression of MMP-2 and MMP-9 in the medium using western blotting which showed reduced expression of MMP-2 in the medium collected from PC-3WAVE-3KD cells." (PMID 26052252, 2015). "MMP-2 and MMP-9 expression levels are also used as biomarkers for prostate cancer malignant progression and therapeutic effects." (PMID 25402510, 2015). "MMP-2 and MMP-9 belong to a gelatinase group of MMPs and their role has been extensively studied in prostate cancer." (PMID 26052252, 2015). "Thus MMP-2 and MMP-9 expression in the tissue and body fluids may be of diagnostic, prognostic and predictive value in the detection and/or clinical monitoring of disease progression and therapeutic efficacy in patients with prostate cancer." (PMID 24978435, 2014). "Our results demonstrated that the expression of VEGF, and the activation of MMP-2 and MMP-9, is closely mediated by oxLDL/LOX-1 in C4-2 prostate cancer cell line." (PMID 25170920, 2014). "Serum MMP-2 and MMP-9 levels were shown to be significantly increased in prostate cancer patients compared to controls." (PMID 24978435, 2014). "Among the diverse members of the homologous MMP family, MMP-2, -7, -9 and MT1-MMP are the most well studied for their roles in prostate cancer progression and thus will be the focus of this review." (PMID 24978435, 2014). "The known transcriptional targets of Pea3 mostly include matrix metalloproteases, such as MMP-2 and MMP-9, identified in the context of breast or prostate cancer models." (PMID 25018694, 2014). "In the current study, we found that restoration of RUNX3 in prostate cancer cells simultaneously up-regulated TIMP-2 expression, which is the negative regulator of MMP-2." (PMID 24475196, 2014). "Western blot was used to examine the TIMP-1, TIMP-2, MMP-2 and MMP-9 expressions in prostate cancer cells." (PMID 24475196, 2014). "This utility has been highlighted by numerous works that have explored the expression of MMP-2 and MMP-9 in serum, urine, and tissues from prostate cancers." (PMID 25097794, 2014). "Matrix metalloproteinase-2 (MMP-2) is a gelatinase and its expression has been reported to be increased in prostate cancer." (PMID 23227342, 2012). "It is interesting to note that hypomethylation of the MMP-2 and MMP-9 genes increases gene expression and contributes to cancer cell invasiveness and tumourigenesis in malignant neoplasms, such as prostate cancer and lymphoma." (PMID 22866959, 2012). "Enhanced expression of MMPs has been correlated with increasing malignancy especially increased expression and activities of MMP-2 and MMP-9 are involved in the process of prostate cancer invasion and metastasis." (PMID 21219645, 2011). "Because MT1-MMP, MMP-2 and MMP-9 are all overexpressed in invasive prostate cancers, it is likely that increased activation of MT1-MMP/MMP-2 complex also activates proMMP-9 and acts as a major mediator of pericellular proteolysis." (PMID 21219645, 2011). "MT1-MMP, MMP-2 and MMP-9 are often overexpressed in advanced prostate cancers and play essential roles in prostate tumor metastasis." (PMID 21219645, 2011). "In the present study, results revealed that PTEN silencing conferred CRC cells with an enhanced invasive capacity to migrate in vitro probably by inducing the expression of MMP-2, MMP-9 and uPA as it has already been observed in prostate cancer cells." (PMID 21203412, 2010). "The distribution and expression of CXCL12, CXCR4, MMP-2 and MMP-9 in human prostate cancer and in tumor cells invading nerve tissue were studied with immunohistochemical staining." (PMID 18983683, 2008). "CXCL12 and its receptor CXCR4 along with MMP-2 and MMP-9 are related with prostate cancer perineural invasion." (PMID 18983683, 2008). "During the process of prostate cancer PNI, MMP-2 and MMP-9 play an important role in degrading the matrix around the tumor and the nerve tissue." (PMID 18983683, 2008).
prostate carcinoma (continued). "The expression of CXCL12, CXCR4, MMP-2, and MMP-9 in human prostate cancer were higher than those in hyperplastic prostate tissues (P < 0.05)." (PMID 18983683, 2008). "Zoledronate as well as alendronate has been found to inhibit secretion and activity of MMP-2 and MMP-9 by tumor cells and tumor-infiltrating macrophages in mouse models of cervical cancer and prostate cancer." (PMID 18371232, 2008). "Our research aims to study CXCL12, CXCR4, MMP-2 and MMP-9 expression in prostate cancer PNI using in vitro experiments, animal model experiments and human prostate cancer tissue." (PMID 18983683, 2008). "The research conducted by the Shafiee group revealed that genistein possesses the capability to reduce MMP-2 expression across a spectrum of human prostate cancer cell lines, spanning from primary noncancerous cells to well-established metastatic variants." (PMID 38939095, 2024). "Moreover, it has also been shown that PMPs can stimulate MMP-2 activation and secretion, MMP-14 expression or MMP-dependent cell migration in lung, breast and prostate cancer." (PMID 36882818, 2023). "In prostate cancer cells, for instance, TGF-β therapy leads to nuclear accumulation of MAPK1, which in turn promotes cancer cell EMT and upregulates the production of MMP1, MMP2/9, and MMP9." (PMID 37817112, 2023). "Of MMPs, MMP2 and MMP9 were the main members presented to be regulated by SKA1 and TRPV2 in some cancers, such as human adenoid cystic carcinoma, non-small cell lung cancer and prostate cancer 20-22." (PMID 35813298, 2022). "Another study related the MMP-2 transcript levels in prostate cancer patients treated or not treated with genistein." (PMID 34336089, 2021). "In addition, FABP4 promotes tumor progression by altering the activities of matrix metalloproteinases (MMPs), especially MMP-2 and MMP-9, in prostate cancer." (PMID 34685761, 2021). "In the process of bone metastasis in lung, breast, and prostate cancer, tumor-driven osteoclastogenic factors, such as TGFβ1, PTHLH (parathyroid hormone-like hormone), and MMP-2 (Matrix metalloproteinase-2), facilitate osteolysis and homing of cancer cells to bone." (PMID 33917757, 2021). "Furthermore, the pro-inflammatory arachidonic acid-derived prostaglandin E2 (PGE2) was shown to enhance the expression of the bone metastasis-promoting proteins MMP2, MMP9, RANKL, and RUNX2 in prostate cancer cells, partly via the PI3K/AKT pathway." (PMID 34064589, 2021). "Moreover, the expression of proliferation-related protein cyclin and migration-related protein MMP2 was evidently down-regulated by silencing lncRNA AGAP2-AS1, which was largely indicative of restrained prostate cancer cell proliferation." (PMID 33101368, 2020). "Employing siRNA-based partial target modulation in DU145 and PC3 prostate carcinoma cells, inhibition of EMT-related gene expression (with downregulation of MMP9, MMP2, VIM, and SNAI1, among others) and suppression of migration and metastasis were assessed in vitro." (PMID 32466621, 2020). "In conclusion, the downregulation of HDGF significantly is associated with the inhibition of the migration and invasion in prostate cancer cells, at least in part, by suppressing EMT process and the expression of MMP9 and MMP2, which play an important role in the tumorigenesis of PCa." (PMID 29300772, 2018). "MMP-2 and MMP-9 destroy ECM and help breast and prostate cancer cells migrate to new places." (PMID 29062841, 2017). "SSX2 knockdown, in the 22Rv1 prostate cancer line, demonstrated a large fold change in many different EMT associated genes (TWIST1, ZEB2, MMP2, VIM, CDH1, CDH2) however these genes did not respond in an anticipated or canonical way." (PMID 27276714, 2016). "Similarly, MMP-2 and -9 levels, as measured in the conditioned media, were significantly reduced in the presence of HI-TOPK-032, in both prostate cancer cell lines." (PMID 25909225, 2015).
prostate carcinoma (continued). "In the present study, we noticed that RUNX3 regulated prostate cancer cell metastasis through MMP-2 but not MMP-9." (PMID 24475196, 2014). "The prostate cancer C4-2 cell line was incubated with increasing concentrations of oxLDL (25, 50, 100 μg/mL) during 12 hours, and the expression of the pro-angiogenic markers VEGF, MMP-2 and MMP-9 was analyzed using real-time PCR." (PMID 25170920, 2014). "The prostate cancer cells models C4-2/LOX-1(−) and C4-2/LOX-1(+) were incubated with 100 μg/mL oxLDL during 12 hours, and expression of the pro-angiogenic markers (VEGF, MMP-2 and, MMP-9) was analyzed." (PMID 25170920, 2014). "Although there is a debate on increased prevalence of high-grade tumors among 5-ARI-treated patients, a recent study showed that finasteride may attenuate tumor aggressiveness and invasion through MMP-2 and MMP-9 downregulation in prostate cancer cells." (PMID 24978435, 2014). "We also confirm, using the aortic ring assay and the chicken embryo CAM xenograft model, that the increase of VEGF, MMP-2 and MMP-9 expression mediated by LOX-1/oxLDL has a tumoral angiogenic effect both in vivo and ex vivo on C4-2 prostate cancer cells models." (PMID 25170920, 2014). "In a follow-up study, IL-10 blocked IGF-1-induced MMP-2 mRNA expression and protein synthesis in primary prostate cells, implying that regulation of MMP expression in prostate cancer cells is a complex interaction of various cytokines present in the tumor microenvironment." (PMID 24978435, 2014). "In addition, in vitro studies also show that the expression of MMP-2 and MMP-9 promote invasion and lymph node metastasis of prostate cancer cells." (PMID 24475196, 2014). "Curcumin suppressed MMP2 and MMP9 activity in the tumor bearing site of prostate cancer." (PMID 24216994, 2013). "In prostate cancer, RhoC promotes tumor metastasis by sequential activation of Pyk2, focal adhesion kinase (FAK), mitogen-activated protein kinase (MAPK) and Akt, followed by the upregulation of MMP2 and MMP9, resulting in the induction of tumor cell invasion." (PMID 23382905, 2013). "Moreover, luteolin reduced cell viability and induced apoptosis in prostate cancer cells, which were correlated with the downregulation of AKT, ERK, mTOR, P70S6K, MMP-2, and MMP-9 expressions." (PMID 23300633, 2012). "MT1-MMP and its substrates pro-MMP-2 and pro-MMP-9 are often overexpressed in a variety of cancers including prostate cancer and the expression levels correlate with the grade of malignancy in prostate cancer cells." (PMID 21219645, 2011). "Inhibition of MMP-2 and MMP-9 expression suppress the metastatic potential of prostate cancer." (PMID 21629786, 2011). "Among them, MMP-2, MMP-9 and MMP-7 play a critical role in prostate cancer progression." (PMID 21629786, 2011). "In prostate cancer cells, down-regulation of MMP9, but not MMP2 is consistent with the loss of the invasion/metastasis phenotype." (PMID 20717117, 2010). "Two MMPs (MMP2 and MMP23) were downregulated in prostate cancer." (PMID 15928670, 2005). "Furthermore, resveratrol inhibited the migration and invasion of prostate cancer cells by promoting demethylation and increasing the expression of tissue inhibitors of metalloproteinases, TIMP2, and TIMP3 and by suppressing the expression of MMP-2 and MMP-9." (PMID 37446252, 2023). "In in vitro tests using prostate cancer cell lines, the BTK inhibitor ibrutinib was found to drastically reduce prostate cancer cell proliferation, wound healing, migration, and invasion, as well as block tumor cell matrix metalloproteinase-2 (MMP-2) and MMP-9 protein production." (PMID 36903645, 2023). "Interestingly, the GHRH antagonist MZ-5-516 in prostate cancer cells, as well as MIA-602, MIA-606 and MIA-690 in non-small cell lung cancer cells, reduced VEGF secretion and attenuated the mRNA expression and activity of MMP2 and MMP9." (PMID 36232554, 2022).
prostate carcinoma (continued). "In prostate cancer, NR2C2 could prevent or delay prostate tumorigenesis via regulating the ATM expression at the transcriptional level and could suppress prostate cancer invasion via altering the TIMP-1/MMP2/MMP9 signals." (PMID 34956884, 2021). "Additionally, invasion-related effectors MMP2, MMP9, and E-cadherin were down-regulated in the miR-124 transfectants, which might account for the impaired invasive and migratory capabilities of prostate cancer cells with miR-124 overexpression." (PMID 25969668, 2015). "Our research demonstrated that the expression of CXCL12, CXCR4, MMP-2, and MMP-9 in prostate cancer was much higher than in hyperplastic prostate tissue, implying that these proteins interact with each other and together may regulate chemotactic ability and invasiveness of tumor cells." (PMID 18983683, 2008). "Moreover, we demonstrated that RUNX3 overexpression inhibited prostate cancer cell migration and invasion resulting from the elevated upregulation of tissue inhibitor of matrix metalloproteinase-2 (TIMP-2), which subsequently inhibited metalloproteinase-2 (MMP-2) expression and activity in vitro." (PMID 24475196, 2014). "Consequently, we try to demonstrate here 3-azidoWA as well as TRAIL mediated inhibition of MMP-2 in cervical (data not shown) and prostate cancer cell line through induction of extracellular Par-4 which has been shown to induce extrinsic apoptotic pathway by FADD-caspase-8-caspase-3 activation." (PMID 22962598, 2012). "In the present study, we demonstrated that MMP-2, MMP-9 and MMP-14 are positive in prostate cancer and its regulators are negative in the majority of cases." (PMID 26742965, 2015). "Our results showed that expression of Snail, MMP-2 and MMP-9 but not Slug is up-regulated in the prostate cancer sections derived from PC3 and LAPC-4 cells overexpressing TIMP-1 when compared to the sections derived from the control PC3 and LAPC-4 cells." (PMID 24143225, 2013). "Not all prostate cancer cells express MMP-2; those which do are able to pass through the basement membrane and the extracellular matrix and enter the circulation; cells that are MMP-2-negative may disseminate in a form of Indian file through the tract left by MMP-2-positive cells." (PMID 40427006, 2025).